B2M (beta-2-microglobulin)
Diseases named in the same sentence as B2M in open-access papers (continued):
Sharing a sentence is not in itself a finding about the gene and the disease.
cancer (continued). "The aims of this study were to evaluate urinary beta-2-microglobulin levels in long-term childhood cancer survivors and determine its relationship with the type of anticancer treatment used." (PMID 34830560, 2021). "This discrepancy hinted towards an anti-cancer immune response and further experiments using T cell depletion and B2m knock out tumor cells confirmed that this drug-induced cancer growth impairment was dependent on T cells and MHC I peptide presentation." (PMID 34711802, 2021). "With more and more attention being paid to the regulatory role of B2M in various cancer types, B2M is considered as a potential mediator for improving the treatment strategy." (PMID 33658560, 2021). "MAP2K1 (also called MEK1) and EGFR were validated as negative regulators by showing that treatment of several cancer cell lines with inhibitors of either enzyme increased mRNA levels and cell surface expression of HLA-A and B2m." (PMID 31112530, 2019). "Through the analysis of copy number alteration of PM samples, we found that there were significant deletions in many genomic regions of PM samples, involving many cancer genes and immune related genes (such as B2M, RHOA, IFNE, JAK1/2, etc.)." (PMID 31570735, 2019). "The functional study of B2M in cancer cells has shown that B2M plays an important role in the promotion of cancer cell growth." (PMID 26983758, 2016). "Western blot analysis showed that the expression of B2M was significant higher in the serous borderline and malignant tumours of the ovary." (PMID 26983758, 2016). "Clinical studies suggest that soluble B2M is a serum marker of the several types of cancers, including OC." (PMID 26983758, 2016). "The high staining of B2M was shown in borderline and malignant tumours, including serous, mucinous, endometrioid and clear cell tumours." (PMID 26983758, 2016). "They include APOA1, VEGFC, YWHAZ, B2M, EIF2S1, CCR9 and many other genes that have been associated with the hallmarks of cancer." (PMID 25986937, 2015). "In contrast, TRPV6 was detected at 7.7±3.0 × 10−2 and 2.38±0.28 × 10−4 the level of B2M in human carcinoma-derived cell lines LNCaP and CaCO-2 respectively." (PMID 22163264, 2011). "Some reference genes such as ACTB and B2M are expressed somewhat more in stomach tissues than in cancer cell lines." (PMID 20507635, 2010). "We examined, in addition to ACTB and GAPDH, four other reference genes, HPRT1, RPL29, 18S rRNA, and B2M that have been evaluated as reference genes in recent studies for other human cancers." (PMID 20507635, 2010). "However, several studies have reported that high immunogenic cancer patients with B2M defect can still exhibit durable responses to anti-PD-1 therapy, suggesting the involvement of immune cell subsets beyond CD8+ T cells in these responses." (PMID 40191187, 2025). "Specifically, 53% (n = 9/17) had no previously reported driver of resistance, and 35% (n = 6/17) had a mutation in a gene previously implicated in acquired resistance (B2M or JAK1/2) that was expected to be deleterious and changed in cancer cell fraction (CCF)." (PMID 39933900, 2025). "Moreover, B2M exhibits significant alterations in cancer tissues, particularly in tumors characterized by microsatellite instability (MSI) and deficient mismatch repair (dMMR)." (PMID 40725113, 2025). "B2M is found both in free form and attached to the cell membrane, and the free form is a significant prognostic factor and predictor of survival in various types of cancer." (PMID 40725113, 2025). "The importance of continued expression of APM genes for prolonged survival is in keeping with the finding that, across a broad range of cancer types, genetic defects in APM, such as loss of heterozygosity of HLA-I and inactivation of B2M, are common mechanisms of immune escape." (PMID 40239619, 2025). "Additionally, in esophageal cancer, miR-148-3p and miR125a markedly depress the expression of MHC-I and B2M, conspicuously curtailing the overall survival of cancer patients." (PMID 40191187, 2025).
cancer (continued). "Additionally, B2M gene alterations can accumulate during cancer progression, contributing to poor reaction to cancer immunotherapies by dampening antigen presentation." (PMID 38888359, 2024). "Downregulation of B2M could decrease antigen presentation to make cancer cells resistant to T cell–directed immunotherapies while simultaneously making them more vulnerable to macrophage attack." (PMID 38483480, 2024). "The principal aim of our study was to explore whether B2M and HLA had utility as a predictive biomarker in early-phase cancer immunotherapy trials." (PMID 38455061, 2024). "To prove that the activation of primary human lymphocytes in TICS was dependent on antigens presented by TNBC cancer cells, we interrupted antigen presentation to CD8+ T cells by either genetic deletion of the B2M gene in cancer cells or by using a blocking antibody against HLA-ABC." (PMID 38678024, 2024). "Due to the absence of these inhibitory ligands, the B2M−/− cancer cells exhibited increased susceptibility to NK cells compared with that of the WT control." (PMID 38638003, 2024). "To determine whether the antitumor effects of the anti-CTLA-4 Ab depends on direct MHC-mediated recognition of cancer cells by T cells, we generated Hepa1-6 #12 cells with beta-2 microglobulin (β2m) or MHC-II expression KO using the CRISPR-Cas9 technique." (PMID 39106430, 2024). "Through the overexpression of anti-phagocytic surface proteins, also known as the “don’t eat me” signal, such as CD47, programmed cell death ligand 1 (PD-L1), and the beta-2 microglobulin subunit of the major histocompatibility class I complex (B2M), cancer cells can evade clearance by macrophages." (PMID 37846296, 2023). "Downregulation of MHC-I molecules, including classical MHC-I and B2M, can be seen in varied cancer." (PMID 38041084, 2023). "This allowed for the first time the identification of mutations associated with acquired resistance to ICB and shown loss of function mutation in IFN signaling (Janus kinase-1 and 2) in two patients and beta-2-microglobulin (B2M) in a third patient in ICB resistant cancer lesions." (PMID 37180110, 2023). "Studies revealed classical MHC-I molecules and B2M may be an immunological prognostic factor for varied cancers." (PMID 38041084, 2023). "Other dMMR/MSI‐associated immune escape mutations that varied in frequency between cancer types included RPL22, which was enriched in EC, and the antigen processing and presentation pathway components B2M, NLRC5, TAP2, and HLA‐B, which were more commonly disrupted in CRC." (PMID 35262923, 2022). "B2M has previously been found to be associated with other non-cardiovascular outcomes, such as various cancers, though not reported in many of the studies included in our review." (PMID 33581388, 2021). "Another relevant positive biomarker for all 18 cancer types is B2M → HLA-F." (PMID 34430923, 2021). "Thus, elevated B2M expression in patients with advanced and localized PCa in contrast to healthy prostate B2M levels justifies the focus on HLA expression in cancer cells as one strategy to prevent immune surveillance." (PMID 34445612, 2021). "B2M mutations have been reported to be associated with prolonged survival for non-metastatic MSI cancer patients." (PMID 34168989, 2021). "We demonstrated that urinary beta-2-microglobulin may play a role in the subtle kidney injury in childhood cancer survivors; however, the treatment-related factors affecting the β2M level remain unknown." (PMID 34830560, 2021). "Likewise, B2M was a hazardous factor in 4 independent cancer types and a favorable factor in 5 independent cancer types in terms of DSS with statistical significance of p < 0.05." (PMID 33658560, 2021). "Among B2M-wild type cancer patients, 7/15 (46.6%) showed therapy response, and 4/15 (26.6%) had SD." (PMID 34168989, 2021).
cancer (continued). "Moreover, in terms of OS, B2M was a hazardous factor in 9 independent cancer types and a favorable factor in 5 independent cancer types with statistical significance of p < 0.05." (PMID 33658560, 2021). "In the duplex format, hsa-miR-486-5p, hsa-miR-451 and B2M were all detected in cancer serum." (PMID 32617186, 2020). "We used qRT-PCR to investigate the expression of HSPs, calreticulin (CALR) (an “eat me signal” molecule expressed in the surface of cancer cells that promotes their removal by cells of the immune system), B2M and SAHAI-01, a classical MHC-I molecule of the Tasmanian devil." (PMID 29702669, 2018). "IL-27 failed only in a cancer cell line bearing a homozygous deletion in the B2M gene." (PMID 27683036, 2016). "Unlike most cancer genes in our network, interface mutations affecting the tumor suppressor beta-2 microglobulin (B2M) were located predominantly on partner genes." (PMID 27043210, 2016). "Accumulating data suggest that B2M may be a biomarker for cancers and a potential target for cancer therapy." (PMID 26983758, 2016). "A high level of soluble B2M is detected in several types of cancers, including breast, colorectal, gastric, lung, oral, ovarian, prostate and testicular cancers, and may be implicated in the immune escape of cancer cells and cancer immunotherapy." (PMID 26983758, 2016). "Thus cancers that have lost B2M still express both membrane and soluble HLA-G molecules able to interact with ILT4." (PMID 26460949, 2015). "The poor efficacy of cancer vaccination administration with ODN1826 adjuvant in MHC-I negative models may be affiliated with B2M deficiency in TC-1 cell lines." (PMID 40191187, 2025). "Nevertheless, cancer vaccines based on T cells may develop resistance because of B2M defect." (PMID 40191187, 2025). "In a subgroup of 19 HLA-A*02:01- and MAGE-A4 double-positive patients, most tumors (63%) were also positive for MHC class I and B2M, indicating that these tumors are competent in antigen presentation which is crucial when targeting intracellular proteins through cancer immunotherapy." (PMID 40151801, 2025). "Finally, we hypothesize that both the binding of B2m-free HCs on the surface of cancer cells to KIRs with long (L) inhibiting sequences (ITIM) may lead to cancer immune escape." (PMID 39057057, 2024). "CD8 T cell numbers in the peripheral blood are not impacted by loss of MHCI expression in cancer cells (mean CD8 T cell number/μl peripheral blood d7 PK5L1940 1010 CD8/μl PK5L1940 B2M−/− 1024 CD8/μl p = 0.87), indicating that there is no systemic loss of CD8 T cells in these mice." (PMID 37072485, 2023). "While analyzing multiple cancer disorders, we found highly variable expression among genes implicated in cancer: EEF1A1, GNAS, NPM1, PIM1, and RHOA are known oncogenes; H3F3A, PTPRC, SMARCB1, and B2M are possible oncogenes; and CASP8, JAK1, and PRKAR1A are known tumor suppressor genes." (PMID 34174938, 2021). "B2M mutations were detected in nearly one‐third of dMMR cancers, none of which recurred." (PMID 31062389, 2019). "Indeed, more and more evidences provide the information that B2M plays a role in cancer biology." (PMID 26983758, 2016). "Interestingly, B2M was found to be inactivated in NHLs and its inactivation has been associated as a mechanism to evade the immune surveillance in DLBCL and other types of cancer." (PMID 24885312, 2014). "Consistently, both genetic or pharmacologic inhibition of EZH2 enhanced H-2Kb and β2M expression and reduced H3K27me3 modification levels on H2K1 and B2m promoter region in RM1 and MC38 cancer cells." (PMID 41252204, 2025).
cancer (continued). "B2M knock out syngeneic models have been shown previously to be resistant to ICI therapy and to possess an immune profile similar to ICI resistant human cancers." (PMID 40321762, 2025). "To ascertain the role of antigen recognition by cancer cells in BLM’s antitumor effects, we conducted knockdown (KD) experiments targeting B2m, a pivotal component of MHC-I molecules, in B16OVA cells." (PMID 39106105, 2024). "To achieve a comprehensive and objective evaluation of MHC-I expression in cancers, we developed a MHC-I signature score based on GSVA of eight MHC-I family genes, including HLA-A, HLA-B, HLA-C, HLA-D, HLA-E, HLA-F, HLA-H, and B2M." (PMID 39408874, 2024). "The cancer cells are able to express a number of signals known as “do not eat me” signals through expression of CD47, CD24, PD-L1, the beta-2 microglobulin (β2M) subunit of MHC-I, stanniocalcin 1 (STC-1) and GD2 to evade the macrophage-mediated phagocytosis." (PMID 38566199, 2024). "Of these genes, TAP2, B2M, IRF1, TAP1, HLA-A, HLA-B and HLA-C were formally and independently classed as CRC drivers, with strongest signals in MSI cancers, but also discovered in MSS cancers (for example, HLA-A and B2M)." (PMID 39112709, 2024). "For instance, B2M, SLPI, BST2, GAPDH, S100A8, S100A9, and HMGB1, despite their beneficial roles in various infections, they contribute to cancer cell proliferation, invasiveness, reduced survival, and increased disease severity across different cancers." (PMID 38589404, 2024). "The triple biomarker combination of B2M, CD8 and PDL1 strongly improved response prediction to cancer immunotherapy." (PMID 38455061, 2024). "It appears that the inverse relationship can also hold true, as the upregulation of the MHC I machinery protein B2M induced EMT in B2M-overexpressing clones of MCF7 (breast), H358 (lung), and SN12C (renal) cancer cells both in vivo and in vitro." (PMID 38067396, 2023). "Similarly, using RNA-seq data, we found that a lower expression of APM-related genes, including B2M, CIITA, ERAP2, TAP2 and TAPBPL, was also associated with a shorter PFS, reflecting the increasing interest in APM biomarkers for clinical outcome and immune escape in cancer." (PMID 37799721, 2023). "Consistent with our finding, individual cancer-specific EMT signature genes such as PDIA3, HLA-A, BCAM, B2M, LGALS3BP, and HLA-C were highly expressed in cancer cells from infiltrated and excluded TMEs." (PMID 38086828, 2023). "The top five ligands targeting CD8+ T-cells by mesenchymal cancer cells from infiltrated tumors were HLA-C, HLA-A, CD59, LGALS3, and B2M." (PMID 38086828, 2023). "MHC I expression can be modulated by cancer cells through DNA hypermethylation, histone deacetylation, and the trimethylation of H3K27 on the promoters of heavy chain, B2M, APM components, and NLRC5." (PMID 38067396, 2023). "B2M of the MHC-I molecules can combine with the inhibitory receptor LILRB1 on the surface of macrophages, protecting cancer cells from phagocytosis." (PMID 38041084, 2023). "Our results reveal hybrid cell upregulation of immune molecules, including CD74, B2M and TNFAIP3, which are known to contribute to cancer cell immune evasion." (PMID 38106024, 2023). "To assess the performance of sABEv3.22 for inducible gene knockout, we targeted two genes expressing Beta-2 microglobulin (B2M) or CD46 regulatory proteins that have been widely studied in the context of allogeneic cell therapies and cancer research." (PMID 37696818, 2023). "Seven reference genes (YWHAZ, GNAS, GAPDH, OAZ1, PTMA, B2M, and ACTB) were screened out among the 95 candidate reference genes from the data set of the platelets’ transcriptome of pan-cancer and 73 commonly known reference genes." (PMID 35770000, 2022). "The overall results indicated that GAPDH, B2M, and ACTB were more stable in each cancer than the other four candidate genes." (PMID 35770000, 2022).
cancer (continued). "ScRNA-seq also demonstrated that CRC cells treated with FTD have a lower expression of HLA-I molecules, B2M, and TAP1, all involved in antigen presentation and commonly downregulated in cancers as a mechanism of immune escape." (PMID 35831404, 2022). "Assessment of genes most upregulated within NHS–rmIL-12–treated carcinoma revealed increased expression of IFN-γ–responsive genes involved in antigen presentation, including B2m, H2-A, Cd74, the immune checkpoint Cd274, and the T lymphocyte chemokine Cxcl9." (PMID 35260537, 2022). "Combining NPG with HO-1 inhibitor demonstrated down-regulation of genes involved in cancer cell invasion and proliferation (EGR1, CXCL2, AREG, CXCL3, EREG, CD3e, CD3g, CD74, and B2M) as compared to NPG or to control animals." (PMID 34066839, 2021). "Whereas the Ct-values between cancer and normal colon tissues varied by about three cycles for GAPDH, β-actin, and PPIA, they were almost identical for B2M (20.20 vs. 20.04)." (PMID 33917056, 2021). "The relationship between beta-2-microglobulin, MHC-I, and cancer immune response needs further exploration, especially in the MSI-H or d-MMR tumors." (PMID 34194441, 2021). "B2M, comprising the light chain of MHC-I molecules, regulates cancer immune escape and metastatic progression." (PMID 33658560, 2021). "The authors postulate that B2M LOH may serve as the initial step towards complete loss of B2M triggered by a second mutation or dysregulation event and provided experimental evidence to demonstrate that cancer cells lacking B2M expression are susceptible to elimination by NK cells." (PMID 34446728, 2021). "To obtain an optimal standardization, we first compared the expression level of the four common housekeeping genes GAPDH, β-actin, B2M, and PPIA in twenty selected cancer and normal colon tissue samples." (PMID 33917056, 2021). "This study investigates EMPD protein expression of targetable B7 family members and cancer/testis antigens (CTAs) B7-H3, B7-H4, PD-L1, PD-L2, MAGE-A, and NY-ESO-1 and components of antigen presenting machinery B2M and MHC-I." (PMID 31692889, 2019). "We used the PLK1 inhibitor (BI2536) to treat cancer cell lines and compared expression levels of MHC class I (HLA-A, HLA-B, HLA-C, B2M, and TAP1 genes and their protein products) between the pre- and post- treated cell lines." (PMID 30631355, 2018). "Moreover, cancer cells may also develop mechanisms to avoid antigen processing and presenting to the cell surface, via silencing or altering the expression of antigen-presenting machinery, beta-2-microglobulin (B2M), or MHC molecules." (PMID 29299180, 2017). "The beta-2 microglobulin was the only transcript common to both APOBEC1 RNA-editing targets and transcripts with greater SBS in healthy than cancer cells." (PMID 23137041, 2012). "Finally, to prove that the increased cancer cell death upon knockdown of circGRAMD4, RBM4 and NBR1 is mediated by increased MHC-I expression on cancer cells, cell surface MHC-I was depleted by knocking down B2M, a critical component of the MHC-I complex." (PMID 40373256, 2025). "Two of the four selected TCRs (TCR1, TCR4) resulted in significant increases in the activation marker CD69 when specifically co-cultured with B2M-transduced, HLA class I-expressing cells but not control or HLA-A2 transduced cancer cells." (PMID 41415427, 2025). "Relevant research demonstrates that B2M LOH is prevalently observed among cancer patients who exhibit poor or no response to ICIs." (PMID 40191187, 2025). "Due to the involvement of leucine-rich alpha-2-glycoprotein and beta-2-microglobulin in various types of cancer and other pathologies, it is not advisable to use these proteins individually for the specific diagnosis of PDAC." (PMID 41009781, 2025). "Moreover, by using the same evaluation criteria, we identify new biomarkers whose impact on drug response spans multiple cancers, including SALL4, B2M, BAP1, CCDC6, ERBB4, FOXA1, GRIN2A, and PTPRT." (PMID 39083502, 2024).